STC1 (stanniocalcin 1)
Diseases named in the same sentence as STC1 in open-access papers (continued):
Sharing a sentence is not in itself a finding about the gene and the disease.
tumor (continued). "STC-1 has previously been shown to be involved in the advancement of aggressive metastasis and invasion by promoting cellular proliferation and reducing apoptosis in many tumor cells." (PMID 34650342, 2021). "STC1 is believed to promote the proliferation of several kinds of tumour cells." (PMID 32468698, 2020). "STC1 is highly expressed in various kinds of tumours at both mRNA and protein levels in the blood and tumour tissues of cancer patients compared with patients with benign diseases and healthy individuals, indicating that it can serve as a potential biomarker for cancer diagnosis." (PMID 32468698, 2020). "However, its role in cancer has attracted much attention, and many studies have shown that STC1 promotes tumour cell viability and proliferation, and facilitates solid tumour invasion and metastasis." (PMID 32468698, 2020). "In addition to the in vitro experiments, an animal study was conducted to elucidate the role of STC1 in cancer-macrophage interaction at the tumor environment." (PMID 33156861, 2020). "The outcome of the interactions could shape therapeutic responses and resistance of cancer cells in TME, indicating the importance of investigating the role of STC1 in tumor-macrophage interaction." (PMID 33156861, 2020). "STC1 promotes tumour metastasis via activation of PI3K/Akt and JNK signalling pathways." (PMID 32468698, 2020). "Such evidence implies that STC1 may have a tumour‐promoting function in most cases, but possesses a tumour‐suppressing trait in a few cases." (PMID 32468698, 2020). "Because STC1 is closely related to hypoxia in the tumour microenvironment, it may be possible that STC1 contributes to the chemoresistance feature of cancers." (PMID 32468698, 2020). "STC1, a central hub gene in F1Gm, may be involved in human ovarian tumorigenesis via promoting proliferation and inhibiting apoptosis of tumor cells." (PMID 32499821, 2020). "Furthermore, immunohistochemistry showed a high level of STC1 protein in 38.9% (89/229) of patients, mainly localized in the cytoplasm of tumour cells." (PMID 32468698, 2020). "An aberrant expression level of STC1 has been found in many kinds of tumours." (PMID 32468698, 2020). "Therefore, STC1 is likely to be an anti‐apoptosis and oncogenic factor because it provides additional energy for tumour cell growth." (PMID 32468698, 2020). "It has been observed that STC1 expression is elevated under hypoxic conditions in tumours." (PMID 32468698, 2020). "Based on these studies, we speculate that overexpression of STC1 is positively correlated with an advanced tumour grade, larger tumour size and deeper tumour invasion with much more distant metastasis." (PMID 32468698, 2020). "STC1 promotes tumour neoangiogenesis that in turn changes the tumour microenvironment." (PMID 32468698, 2020). "We observed that the injection of 50 ng/kg sevoflurane significantly reduced the tumor volume compared with the NC group, while the anti-tumor effect of sevoflurane could be partly reversed by up-regulation of STC1." (PMID 31889892, 2019). "However the same set of date showed tumors with greater expression level of STC1 (tumor/normal ≥ 2) being significantly smaller (p = 0.008) than the samples with lower STC1 (tumor/normal < 2)." (PMID 29467934, 2018). "The underlying mechanisms of a greater STC1 expression in the smaller tumor mass of HCC is not clear." (PMID 29467934, 2018). "Furthermore, ANGPLT4 played a critical role in regulating tumor cell proliferation and angiogenesis, possibly by regulating STC1, EPHA3 and TNFSF14 genes." (PMID 28903395, 2017). "Furthermore, analysis of the relationship between STC1 expression and T1 stage ccRCC tumor size revealed that STC1 mRNA levels correlated with average tumor diameter (n = 106, r = 0.215, P = 0.027)." (PMID 25740019, 2015).
tumor (continued). "Although the greater expression levels of STC1 in tumor samples could be interpreted as its pro-oncogenic role in tumor progression, the counteracting effects STC1 on the pro-inflammatory effects of IL6 and IL8 might slow down the process of carcinogenesis." (PMID 26469082, 2015). "Inconsistencies regarding the effect of STC1 on cancer cell proliferation may be owing to the different mechanisms exploited by tumor cells to promote growth and survival." (PMID 25740019, 2015). "Nonetheless, the underlying mechanism on how STC-1 reduced tumor growth has not been revealed in this study." (PMID 26469082, 2015). "We attempted to delineate the possible factors that might be involved in STC1-mediated reduction in tumor size." (PMID 26469082, 2015). "STC1 expression in tumor tissues significantly correlated with clinical stage." (PMID 24743310, 2014). "Thus, further studies are to elucidate deeply the mechanisms involved in STC1-mediated inhibiting of tumor progression and to further explore what other molecules take part in the progression." (PMID 23382863, 2013). "STC-1 mRNA detected in PB and/or BM was closely associated with its protein high/moderate expression in parallel tumor tissues, regardless of clinical staging." (PMID 22537917, 2012). "Stanniocalcin-1 (STC-1) is a potential marker of disseminated tumor cells (DTCs)." (PMID 22537917, 2012). "Furthermore, we reported enhanced expression of STC1 in tumor tissues compared to the background normal tissues." (PMID 22200953, 2012). "Previous studies have shown stanniocalcin-1 (STC-1) may be a promising tumor marker, for its high expression level in various of malignancies including ESCC, as compared with adjacent normal tissues." (PMID 22537917, 2012). "The in vivo and in vitro experiments suggest that STC-1 may promote tumorgenesis through other mechanism, other than tumor cell proliferation itself." (PMID 21672207, 2011). "Therefore, we hypothesised that circUBA2 affects the CSC-like properties of GC and thus tumour progression through upregulation of STC1 expression." (PMID 39103836, 2024). "Similarly, STC1 may participate in tumor progression by affecting the polarization state of macrophages (M1 anti-tumor or M2 pro tumor)." (PMID 39201771, 2024). "So, S100A4 may also mediate the regulatory function of STC1 on the tumor microenvironment." (PMID 37400459, 2023). "Thus, we concluded that STC1 promoted tumor metastasis and lipid metabolism in vitro." (PMID 35392966, 2022). "Besides, STC1 also could enhance tumor angiogenesis via activation of the VEGF/VEGFR-2 signal pathway." (PMID 35273656, 2022). "STC1 may play a regulatory role in different tumors as a tumor suppressor." (PMID 34663825, 2021). "Furthermore, weaker STC-1 expression was seen in epithelium of EC with a higher grade (p = 0.030), LVSI (p = 0.050), deep myometrial invasion (p = 0.003), large tumour size (p = 0.001), and MMR deficiency (p = 0.048), suggesting a protective role of STC-1 in EC." (PMID 34650342, 2021). "It was verified that STC1 could accelerate tumor growth and reduce disease-free survival in mice." (PMID 32286381, 2020). "Because tumor size is primarily determined by the proliferation of cancer cells, we sought to verify whether the larger tumor size which was observed in metastatic ccRCC was a result of elevated STC1 expression." (PMID 25740019, 2015). "Because tumor size primarily determined by the proliferative ability of tumor cells, we examined whether the larger tumor size observed in metastatic ccRCC was a result of high levels of STC1 expression." (PMID 25740019, 2015). "Although the underlying mechanistic actions of STC1 on tumor progression are not immediately obvious, a considerable number of experimental studies using different cancer cell lines demonstrated that STC1 was involved in Warburg effect, apoptosis, angiogenesis, and wound healing." (PMID 26469082, 2015). "STC1 or STC2 status may play important roles in tumor biology." (PMID 24743310, 2014).
tumor (continued). "This indicated that STC-1 may promote the tumor growth in vivo depended on tumor angiogenesis." (PMID 21672207, 2011). "Therefore, we speculated that STC-1 might regulate the tumor development through enhancing tumor angiogenesis." (PMID 21672207, 2011). "Histological and multiplex immunofluorescence analyses confirmed that NSUN2 deletion reduced tumor-induced PNI and downregulated CDCP1 and STC1, while lactate supplementation increased pan-lactylation, NSUN2, CDCP1, and STC1 expression." (PMID 41356184, 2026). "Genetic or pharmacological inhibition of STC1 suppresses NF‐κB‐mediated EMT, reduces tumor invasion, and restores TMZ sensitivity in GBM models." (PMID 41020346, 2025). "eATP also consistently upregulates Stanniocalcin-1 (STC1), a gene that significantly contributes to EMT, CSC formation, and tumor growth." (PMID 38380370, 2024). "We recently reported that the protein STC1 significantly contributes to CSC formation and tumor growth." (PMID 38380370, 2024). "Numerous studies have also explored the intriguingly complex roles of both STC1 and STC2, identifying them as potential universal tumor biomarkers and promising therapeutic targets across various cancers, including those affecting female reproductive tissues." (PMID 39186548, 2024). "Stanniocalcin-1(STC1)is ubiquitously expressed in human body, which is proven to involve with tumor progression and clinical prognosis." (PMID 39654892, 2024). "Through analysis of the HPA database, we recognized remarkably higher expression levels of specific proteins, including AQP1, ITGA5, MAP3K8, PIK3R3, STC1, and TGM2, in HNSCC tumor tissues." (PMID 38688945, 2024). "Among cellular genes in both GI and skin KS lesions as compared to their respective normal tissues, both FLT4 and STC1 were increased." (PMID 37740179, 2023). "STC1 was selected for further investigation due to the correlation between total KSHV gene expression and STC1 expression in GI and skin KS." (PMID 37740179, 2023). "The level of STC‐1 in the peripheral plasma was significantly correlated with the T stage, N stage, clinical stage, grade, hormone receptors, HER‐2 status, and tumor subtype." (PMID 36336967, 2023). "In summary, we found that CAF-secreted STC1 promoted HCC stemness and STC1 expression was positively related to Notch1 expression, poor prognosis, and advanced tumor stage in HCC." (PMID 37004088, 2023). "A high level of STC1 was positively correlated with advanced tumor stage (stage III/IV) and high tumor grade (grades 2–3), while a low level of STC1 was positively correlated with early tumor stage (stage I/II) and low tumor grade (grades 1)." (PMID 35392966, 2022). "For example, stanniocalcin 1 (STC1), an intracellular checkpoint, can trap DAMPs (e.g., calreticulin (CRT)) and inhibit DC phagocytosis and T-cell activation, contributing to tumor immune escape." (PMID 33859752, 2021). "By targeting STC‐1‐positive cells, we induced a significant growth‐arresting effect toward STC‐1‐negative tumor cells and confirmed that the UPRT/5‐FU system exhibits a significant bystander cytotoxic effect both in vitro and in vivo." (PMID 33826244, 2021). "We show that after coculture of canine fibroblasts with the tumour cell line C2, miR‐27a is downregulated, while expression of CAF markers ACTA2 and stanniocalcin 1 confirmed the activation of fibroblasts." (PMID 32133790, 2020). "The expression of stanniocalcin-1 (STC1), a glycoprotein involved in calcium/phosphate homeostasis, is enhanced in hypoxic conditions and promotes tumor cell invasion and resistance to cisplatin." (PMID 32751679, 2020). "In the future, it will be interesting to further examine the roles of these novel STC1 interactions in TAM maturation and tumor development." (PMID 32579928, 2020). "In contrast, overexpression of STC1 in normal prostate cell line RWPE‐1 and xenografted tumours promotes cell growth." (PMID 32468698, 2020).
tumor (continued). "Our recent study demonstrated that STC1 overexpression in HCC inhibited p70S6K/p-rpS6 signaling and energy metabolism to reduce tumor growth." (PMID 33156861, 2020). "Among these DEGs several genes with oncogenic and/or metastasis promoting function (e.g. STC1, YES1, PORCN) were found to be down-regulated and certain tumour suppressor genes (e.g. DKK1, PERP) showed overexpression in LINC00152-silenced cells." (PMID 32307642, 2020). "STC1 increases both the mRNA and protein levels of eNOS, VEGF and VEGFR2, and stimulates the VEGF signalling pathway, which subsequently enhances tumour angiogenesis." (PMID 32468698, 2020). "However, the underlying molecular mechanism on how STC1 reduced tumor masses is not clear." (PMID 29467934, 2018). "Numerous studies have examined STC1 and STC2 in the tumor microenvironment, where they have positive effects on tumor migration and invasion." (PMID 29748538, 2018). "CAFs also secrete factors including VEGF, CXCL12, FGF, IL-8/CXCL8 and PDGF to stimulate tumor angiogenesis, CAFs release factors such as HGF, CCL5 and stanniocalcin 1 (STC1) to stimulate tumor invasiveness and metastasis." (PMID 29383119, 2017). "Our data suggested that STC1 inhibited pro-migratory effects of IL6/IL8 and enable apoptotic pathways in tumor cells to reduce growth and metastasis of HCC." (PMID 26469082, 2015). "This assumption is supported by our in vitro HCC cell-line studies in which STC1 inhibited the pro-migratory effects of IL6 and IL8, and reduced sizes of tumor spheroids." (PMID 26469082, 2015). "Particularly, a significant reduction in tumor sizes was shown in STC1/IL-8-High tumor (31% reduction versus STC1/IL-8-Normal, p = 0.025), but not in STC1/IL-6-High cases (22% reduction versus STC1/IL-6-Normal, p = 0.245), which may due to the small sample size of the STC1/IL-6-High cohort." (PMID 26469082, 2015). "Lentiviral-based STC1 overexpression in Hep3B and MHCC-97L cells however showed inhibitory action on the pro-migratory effects of IL-6 and IL-8 and reduced size of tumor spheroids." (PMID 26469082, 2015). "Using a cohort of patients with HCC (n = 216), the STC1 gene expression level was examined in paired HCC normal (N) and tumor (TU) tissues by microarray." (PMID 26469082, 2015). "Recent studies demonstrate that mammalian STCs (STC1 and STC2) play important roles in tumor progression." (PMID 24743310, 2014). "Some clinicopathological studies correlate high expression levels of STC1 and STC2 in human tumor samples with poor prognostic outcomes." (PMID 24743310, 2014). "Based on these results, STC1 expression is thought to be related to the Warburg effect, in which HIF-1α plays a key role in modulating glycolytic enzymes and reprogramming of tumor metabolism." (PMID 22200953, 2012). "We observed increased mRNA expression for STC1 and LOXL2 in tumour tissue, consistent with previous reports." (PMID 18590575, 2008). "In lung cancer, STC1 expression is negatively correlated with immunotherapeutic effects and contributes to anti-tumor immune cell activity in the tumor microenvironment (TME) by affecting tumor immune evasion and immunotherapy resistance." (PMID 40741411, 2025). "While this study examined the correlation between STC1 expression and tumor-infiltrating immune cells within the TME, it did not explore the spatial relationships or functional interactions between STC1 and immune cells." (PMID 40741411, 2025). "Additionally, immunohistochemistry (IHC) staining, qRT‐PCR, and western blot were used to investigate the expression of STC1 in GBM tissues and non‐tumor controls." (PMID 41020346, 2025). "STC1 promotes GBM progression and temozolomide (TMZ) resistance by activating the NF‐κB signaling pathway, which drives epithelial–mesenchymal transition (EMT) and enhances tumor aggressiveness." (PMID 41020346, 2025).
tumor (continued). "We also found that circUBA2 could upregulate STC1 expression via miR-144-5p sponging and further activates the IL-6/JAK2/STAT3 signaling pathway, thereby promoting stemness and tumour progression in GC in vivo and in vitro." (PMID 39103836, 2024). "STC1 is also involved in the regulation of key signaling pathways, including PI3K/Akt and JNK/AP1, which are critical for cancer cell survival and adaptation to hypoxic conditions within the tumor microenvironment." (PMID 39668832, 2024). "As described, FGFBP1, STC1, and NPNT proteins have tumor‐promoting effect thus, downregulation of these proteins could have contributed to the synergistic effect in our study." (PMID 38217262, 2024). "Furthermore, we identified STC1 as a critical component of the RRGS, playing a significant role in tumor progression and immune evasion." (PMID 39668832, 2024). "First, we checked the roles of STC1 on tumor cell–innate malignancy and noticed that cell proliferation was not affected after recombinant human STC1 (rhSTC1) treatment." (PMID 37400459, 2023). "STC1 might serve as a potential biomarker for the prognostic assessment of HCC, and the stromal-tumor amplifying STC1-Notch1 feedforward signal could constitute an effective therapeutic target for HCC patients." (PMID 37004088, 2023). "Using the Xenograft mice model, we confirmed that the tumor-killing efficacy of CAR-T could also be inhibited by hMSCs in vivo, whereas knockdown of STC1 effectively abolished the inhibition." (PMID 36779699, 2023). "Together, these results strongly suggest that the KO of STC1 resulted in fewer CSC cells in the tumors, consistent with our hypothesis that STC1 participates in CSC formation and therefore tumor growth." (PMID 36499099, 2022). "STC1 and other genes constitute a molecular network, which endows CRC with chemoresistance.VIP can regulate the growth and function of various immune cells and tumor cells." (PMID 35252182, 2022). "Using HCC cell-line analysis, we showed that STC1 exerted inhibitory action on the growth of tumor spheroids in culture, reduced the pro-migratory effects of IL-6/IL-8 on HCC, and diminished the development of tumor mass in nude mice model." (PMID 33156861, 2020). "When the non-IMC fraction was enriched for either AT2/tumor cells or fibroblasts by short-term culture, Stc1 gene expression was predominantly detected in the fibroblast cultures." (PMID 32579928, 2020). "After optimization of our protocol, we were able to establish three independent tumor cell lines from the Stc1+/− SPK lung, whereas attempts to generate tumor cell lines from the Stc1+/+ SPK lung were not successful." (PMID 32579928, 2020). "Such examples indicate that STC1 is an intermediate modulated by many tumour‐related factors rather than a determining factor in tumorigenesis, causing it plays distinct functions in different kinds of cancers." (PMID 32468698, 2020). "The results revealed that hypoxia stimulated cells to synthesize EVs proteins involved in enhancing tumour cell proliferation (NRSN2, WISP2, SPRX1, LCK), metastasis (GOLM1, STC1, MGAT5B), stemness (STC1, TMEM59), angiogenesis (ANGPTL4), and suppressing host immunity (CD70)." (PMID 33050615, 2020). "Notably, STC1 is a downstream target gene of HIF-1α, the key transcriptional factor mediating inflammatory responses and tumor transformation." (PMID 33156861, 2020). "Nevertheless, the relating effects of STC1 and anti-/pro-inflammatory environment on tumor development were not revealed." (PMID 33156861, 2020). "However, the Stc1+/− SPK tumor cell lines expressed much lower levels of Stc1 mRNA than Stc1+/− SPK fibroblasts, demonstrating that, as with the BVE model, Stc1 is predominantly expressed from lung fibroblasts in the SPK model." (PMID 32579928, 2020).